G6PD (glucose-6-phosphate dehydrogenase)
Diseases named in the same sentence as G6PD in open-access papers (continued):
Sharing a sentence is not in itself a finding about the gene and the disease.
hemolysis (19 papers, 2010 to 2026). Disruption of the integrity of the erythrocyte membrane causing release of hemoglobin. "All subsequent results are restricted to the 101 patients with probable or possible severe PQ-related hemolysis, 95 of whom were G6PD deficient (<30%)." (PMID 37604475, 2023). "Gradual plasma glucose correction to avoid rapid decrease in glucose availability for red blood cells is likely to reduce the occurrence of hemolysis in G6PD-deficient patients." (PMID 36008815, 2022). "Three G6PD gene mutations were found in 4 hemolysis patients: c.1376G > T, c.1388G > A and c.95A > G." (PMID 35313968, 2022). "As shown for dapsone, and likely to be the case with primaquine and tafenoquine, in G6PD-deficient individuals, hemolysis and AHA result from a more complex parasite/drug/host interaction." (PMID 28749773, 2017). "Glucose-6-phosphate dehydrogenase (G6PD) deficiency anemia is associated with intravascular hemolysis." (PMID 27648201, 2016). "Glucose-6-phosphate dehydrogenase (G6PD) enzyme deficiency is one of the prevalent disorders in Guilan province, northern Iran, causing many patients to suffer from acute hemolysis." (PMID 25002925, 2014). "Among the rarest cases, ATIN induced by a kidney-limited sarcoidosis, G6PD patient with hemolysis induced ATIN, and isolated ATIN induced by ANCA-associated vasculitis (AAV) with positive C-ANCA, which the latter representing the first case in our country and the fourth case worldwide." (PMID 40000970, 2025). "In this series, a rare case of G6PD patient presented with gallstone pancreatitis that induced intravascular hemolysis and AKI." (PMID 40000970, 2025).
acute kidney injury (18 papers, 2012 to 2026). Sudden and sustained deterioration of the kidney function characterized by decreased glomerular filtration rate, increased serum creatinine or oliguria. "It is important to know that MB is contra-indicated together with serotonergic drugs, in glucose-6-phosphate dehydrogenase deficient patients, in patients with renal failure, and in pregnant women." (PMID 38727831, 2024). "It has been reported that an overdose of NAC (100 g) in a short time can cause hemolysis, thrombocytopenia, acute renal failure, and death in patients with glucose-6-phosphate dehydrogenase (G6PD) normal." (PMID 34208683, 2021). "In a case series of G6PD deficient Brazilian patients with P. vivax administered daily 0.5 mg/kg primaquine, among those with a creatinine measurement 5/16 (31%) developed acute kidney injury." (PMID 28356147, 2017). "Although G6PD has a good overall prognosis, attention must be paid to acute renal failure as a significant complication arising from severe hemolysis, potentially leading to acute tubular necrosis." (PMID 40527851, 2025). "In a similar regimen, 18 G6PD-deficient patients presented with AHA that required red blood cell transfusions and finally developed acute renal failure." (PMID 24568147, 2014). "Naphthalene use has been associated with intravascular haemolysis especially in patients with glucose-6-phoshate dehydrogenase (G6PD) deficiency but its unorthodox use for the treatment of urethritis in a young man and its associated acute kidney injury has not been described in Ghana." (PMID 31312313, 2019). "The high frequency of G6PD can suggest that G6PD may be high in Congolese population and needs a screening programme to prevent an acute intravascular haemolysis leading sometimes to renal failure." (PMID 23767699, 2013).
Alpha-thalassemia (18 papers, 2007 to 2025). Alpha-thalassemia is an inherited hemoglobinopathy characterized by impaired synthesis of alpha-globin chains leading to a variable clinical picture depending on the number of affected alleles. "Although they had varied topographical distributions, alpha-thalassemia trait and Glucose-6-Phosphate Dehydrogenase Deficiency (G6PD) were frequently observed alongside sickle cell illness in children aged 0–24 months." (PMID 40029835, 2025). "The authors showed that the most important red blood cell polymorphism was heterozygous α+-thalassemia (37.8%), followed by G6PD A deficiency (16.4%), heterozygous sickle cell trait (15.9%), and G6PD A- deficiency (13.5%), and homozygous α+-thalassemia (5.2%)." (PMID 40225210, 2025). "Model covariates are SCT; Sickle cell trait (Hb AS), Hb AA; Sickle cell normal: Alpha thalassemia variants (αα/αα, -α3.7/αα), G6PD African variant: B; WT, A-; (202 C > T/376T > A), A;(376T > A)." (PMID 37340364, 2023). "P. falciparum exerts strong selection pressure on sickle cell trait (SCT), alpha thalassemia (-α3.7/αα), glucose-6-phosphate dehydrogenase (G6PD), and merozoite surface protein 2 (MSP-2) variants (FC27, 3D7) that confer reduced malarial disease severity." (PMID 37340364, 2023). "The evidence on the role of alpha‐thalassemia and glucose‐6‐phosphate dehydrogenase (G6PD) deficiency in the development of stroke in children with SCA is conflicting." (PMID 33938598, 2021). "Thus, this study investigated the association of alpha‐thalassemia and G6PD(A−) variant with abnormal TCD velocities among Nigerian children with SCA." (PMID 33938598, 2021). "Coinheritance of alpha-thalassemia deletions and glucose-6-phosphate deficiency (G6PD) may affect the degree of anemia whilst alpha-thalassemia status modifies red cell indices and rheology, as can iron status." (PMID 23691341, 2013). "Moreover, Hakka population has variations of G6PD polymorphism, and higher prevalence of alpha-thalassemia than Hokkien Also, between Hakka and Hokkien populations, the Hakka appeared to have a higher frequency of paraoxonase (PON) activity than Hokkien." (PMID 17573960, 2007). "Co-inheritance of alpha-thalassemia is protective against elevated cerebral blood flow velocities in children with SCA and is associated with reduced stroke risk, whilst G6PD increases the risk." (PMID 23691341, 2013). "Alpha thalassemia (alpha-thal) and G6PD genotypes were evaluated by PCR." (PMID 30204801, 2018). "The other gene variants – including G6PD, blood type, alpha thalassemia, HO-1, and SLCO1B1 – did not carry significant difference." (PMID 30287871, 2018). "With an alpha thalassaemia frequency of 0·68; SAO frequency of 0·07, and G6PD deficient X chromosome frequency of 0.13, all entirely plausible for the Madang region of Papua New Guinea, the sensitivity of the OTOFT for beta thalassaemia drops to 0.74 in females and 0.69 in males (Fig4 marker A)." (PMID 25521998, 2015). "Furthermore, our data showed the other common gene variants related to bilirubin production – including G6PD, blood group, and alpha thalassemia – were not relevant to prolonged jaundice." (PMID 30287871, 2018).
glioblastoma (18 papers, 2017 to 2025). The most malignant astrocytic tumor (WHO grade IV). "Hypoxia and activation of the pentose phosphate pathway (PPP), as well as overexpression of glucose-6-phosphate dehydrogenase (G6PD), are hallmark features of glioblastomas (GBM), contributing significantly to tumor progression metabolic adaptation and drug resistance." (PMID 41009654, 2025). "Inhibition of the PPP enzyme, G6PD, by 6-AN, inhibited proliferation of glioblastoma cells and colony formation in embryonic stem cells." (PMID 37258701, 2023). "Our previous studies showed that hirsutinolides inhibit the expression of G6PD and TrxR1 in human glioblastoma models." (PMID 36473850, 2022). "One of the main erasers of m6A, ALKBH5, which is upregulated in glioblastoma cells, demethylated glucose-6-phosphate dehydrogenase (G6PD) mRNA, promoting the translation and activation of the pentose phosphate pathway (PPP)." (PMID 36012529, 2022). "Furthermore, Fyn expression, malignancy, and prognosis are correlated with G6PD pY481 in human glioblastoma." (PMID 39697541, 2024). "Furthermore, four abnormally expressed metabolic enzymes that directly regulate metabolites (GLS, GDH1, HK2 and G6PD) were downregulated by Chr-A in glioblastoma cells." (PMID 39330272, 2024). "Besides, high expression of G6PD can also promote the growth of glioblastoma and inhibit its senescence." (PMID 37352167, 2023). "In addition, we found that H6PD, but not G6PD, was associated with a poor survival rate for glioblastoma patients." (PMID 33723244, 2021). "Several studies have probed the contributions of glucose-6-phosphate dehydrogenase and 6-phosphogluconate dehydrogenase to NADPH production and have identified these enzymes as therapeutic targets for cancer, including glioblastoma." (PMID 33937017, 2021). "At the transcriptional level, treatment with the nitrocompounds resulted in the downregulation of G6PD, SIRT2, and VEGF gene expression, which may contribute to reduced glioblastoma cell proliferation and impaired adaptation to hypoxic stress." (PMID 41009654, 2025). "Four abnormally expressed metabolic enzymes, glutaminase (GLS), glutamate dehydrogenase 1 (GDH1), hexokinase 2 (HK2) and glucose-6-phosphate dehydrogenase (G6PD), which directly affect metabolites in certain pathways, were found to be downregulated by Chr-A in glioblastoma cells." (PMID 39330272, 2024). "Moreover, a recent study on glioblastoma found that the phosphatidylinositol 3-kinase enhancer A (PIKE-A) mediates the binding of the signal transducer and activator of transcription 3 (STAT3) with the G6PD promoter, leading to enhanced G6PD expression." (PMID 38139067, 2023). "Interestingly, PIKE-A increases the growth of glioblastoma and suppresses cellular senescence by triggering the Fyn-mediated STAT3 signalling pathway, which increases the activation of the pentose phosphate pathway (PPP), promotes G6PD expression, and increases DNA synthesis and ROS detoxification." (PMID 39697541, 2024).
ovarian carcinoma (18 papers, 2015 to 2024). A malignant neoplasm originating from the surface ovarian epithelium. "The expression levels of carboplatin resistance-associated proteins, AKR1B1, ITGAV, TGFβ1 and G6PD, in platinum resistant and relapsed human ovarian cancer samples are consistent with our observations in vitro data on control and carboplatin-resistant cells." (PMID 36463238, 2022). "A recent study utilizing ovarian cancer patient-derived spheroids also reported significant association between cisplatin resistance, elevated levels of G6PD and enhanced level of GSH-producing enzymes in resistant cells." (PMID 36463238, 2022). "Cisplatin resistance in ovarian cancer was associated with increased expression and activity of glucose-6-phosphate dehydrogenase (G6PD), which enabled greater NADPH production via the PPP for redox homeostasis." (PMID 33092283, 2020). "Interestingly, resistance to cisplating was linked to glucose-6-phosphate dehydrogenase (G6PD) and glutathione-producing redox enzymes in PDOs from different types of ovarian cancers." (PMID 37760571, 2023). "G6PD is detected in the exosome and mediates metabolic transformation that accounts for tumor development in two late-stage ovarian cell lines, and it could act as a diagnostic, poor prognostic and therapeutic target of late-stage ovarian cancer." (PMID 35207558, 2022). "Blocking STAT3 decreased G6PD mRNA expression and increased the sensitivity of paclitaxel resistant ovarian cancer cells to paclitaxel." (PMID 36902166, 2023). "The inhibition of glucose 6-phosphate dehydrogenase (G6PD) has been shown to reduce omental metastasis of ovarian cancer cells, thus suggesting a role of PPP in peritoneal metastasis of ovarian cancers." (PMID 37233659, 2023). "In summary, their research reveals overexpression of STAT3 increases ovarian cancer colony formation, proliferation, and resistance to paclitaxel by increasing G6PD expression and pentose–phosphate metabolism flux." (PMID 36902166, 2023). "Paclitaxel-resistant ovarian cancer cells showed an enhanced PPP flux in which G6PD was overexpressed." (PMID 35207558, 2022). "Glucose-6-phosphate dehydrogenase (G6PD) levels are higher in paclitaxel resistant ovarian cancer cells compared to that of paclitaxel sensitive cancer cells." (PMID 34575100, 2021). "Depletion of G6PD in the paclitaxel resistant ovarian cancer cells increases its sensitivity to the paclitaxel treatment." (PMID 34575100, 2021). "These low levels of PRMT6 lead to reduction of the repressive H3R2me2a modifications in the promoter region of G6PD resulting in the enhanced expression of G6PD which contributes to the paclitaxel resistance of the ovarian cancer cells." (PMID 34575100, 2021). "The higher expression and activity of G6PD is also verified on another ovarian cancer cell line, also cisplatin resistant, SKOV3/DDP." (PMID 32023830, 2020). "Of note, elevated expression of SLC2A1 and G6PD, as well as increased PPP and OXPHOS activity, have recently been linked with resistance of putative ovarian cancer stem cells to glucose deprivation." (PMID 28412735, 2017). "Aur promotes activation of NRF2, a key transcriptional factor that upregulates enzymes involved in antioxidant metabolism such as TrxR, sulfiredoxin, glutamate cysteine ligase, glutathione S-transferase, and glucose-6 phosphate dehydrogenase in ovarian cancer A2780 cells." (PMID 39288141, 2024). "The OS of ovarian cancer patients prolonged with the high-expression of ATG7, G6PD, SLC3A2, MAP1LC3C and PTGS2, but shrank with the increased expression of NFS1, VDAC2, ACSL3." (PMID 35039008, 2022). "Short-term glucose starvation in ovarian cancer cells was shown to upregulate SLC2A1 and G6PD mRNA and protein levels." (PMID 28412735, 2017). "In line with a published study on ovarian cancer stem cells that are more resistant to glucose deprivation, glucose-restricted OVCAR3 cells induced G6PD and SLC2A1 expression at the transcriptional level." (PMID 28412735, 2017).
ovarian carcinoma (continued). "Considering this, we sought to determine whether HSP27-knockdown ovarian cancer cells decrease levels of GSH and G6PD when treated with cisplatin." (PMID 37628819, 2023). "In this view, a liposomal formulation of cisplatin was studied for prolonged pharmacokinetics of the drug in combination with 6-AN, an inhibitor of the enzyme G6PD (the rate-limiting step of the PPP), to restore the sensitivity of resistant cisplatin ovarian cancer cells." (PMID 32023830, 2020). "However, no prognostic role of AKRIBI, ITGAV and G6PD was evident in TCGA data and GSE (from Gene Expression Omnibus) datasets which included 738 high grade ovarian cancer patients that had undergone chemotherapy treatments." (PMID 36463238, 2022).
asthma (17 papers, 2007 to 2025). "Asthma was slightly more frequent among G6PD deficient individuals (OR 1.08, 95% CI 1.00 to 1.16, P=.043)." (PMID 37753082, 2023). "The increased risk of asthma among G6PD-deficient subjects was observed in both sexes, although statistical significance was reached in only the female subgroup." (PMID 34884340, 2021). "An additional epidemiological study in southern Italy, including Sardinia and Sicily, reported a prevalence of asthma ranging between 2.6% and 3.2%, making the island the ideal model to test the G6PD/asthma association." (PMID 34884340, 2021). "The unadjusted risk of asthma was significantly higher than the unity among G6PD-deficient patients (1.69, 95% CI 1.31–2.17)." (PMID 34884340, 2021). "Twenty-nine subjects (2.92%) had underlying diseases, including asthma, unspecified headache, dyspepsia and glucose-6-phosphate dehydrogenase (G6PD)." (PMID 32507108, 2020). "Amongst them, an overwhelming majority of students (N = 400, 88.9%) considered themselves healthy, while some (N = 10, 2.2%) had glucose 6–phosphate dehydrogenase (G6PD) deficiency and asthma (N = 8, 1.8%)." (PMID 28970463, 2017). "However, there was no remarkable change in glucose-6-phosphate dehydrogenase deficiency (G6PD) and asthma patients’ admissions between pre-COVID-19 and during COVID-19 study periods." (PMID 39252732, 2024). "In asthma, the level of reduced glutathione is significantly increased, and G6PD-deficient subjects’ insufficient production of NADPH may contribute to asthma pathogenesis." (PMID 37753082, 2023). "However, a retrospective case-control study showed that G6PD deficiency is an independent risk factor for asthma and G6PD was noticeably downregulated in asthmatic children." (PMID 37753082, 2023). "Interestingly, the proportion of asthma sufferers was higher among G6PD-deficient patients than among patients with normal enzyme activity (5.8% vs. 3.6%, p < 0.0001) in both males (6.4%) and females (4.3%)." (PMID 34884340, 2021). "Interestingly, several years ago, a few studies reported an increased risk for developing asthma in subjects carrying a glucose-6-phosphate dehydrogenase (G6PD) defect." (PMID 34884340, 2021). "The common medical conditions were ranked as follows: allergy (6.7%), asthma (4.1%), hernia (1.5%), Glucose-6-phosphate dehydrogenase deficiency (G6PD, 1.3%), heart disease (0.8%), renal disease (0.6%), tuberculosis (0.6%), hepatitis (0.4%), and epilepsy (0.3%)." (PMID 18158857, 2007). "Thus, it is reasonable to speculate that G6PD-deficient subjects may have insufficient production of NADPH to maintain adequate GSH stores in asthma patients." (PMID 34884340, 2021). "Therefore, this population is an ideal model to test the hypothesis of the G6PD/asthma association with an adequate degree of statistical power." (PMID 34884340, 2021). "CYBB (AUC ═ 0.82), EPAS1 (AUC ═ 0.839), CBS (AUC ═ 0.804), G6PD (AUC ═ 0.86), and STAT3 (AUC ═ 0.873) demonstrate high diagnostic accuracy for asthma (AUC > 0.8)." (PMID 40165005, 2025). "In conclusion, CYBB, EPAS1, CBS, G6PD, and STAT3 demonstrate strong diagnostic potential for asthma." (PMID 40165005, 2025). "To confirm the DEP in the LC-MS/MS experiment, we used an ELISA experiment and choose a key protein G6PD, which is decreased in asthma reported by studies from other groups." (PMID 33194371, 2020). "The association of asthma with the G6PD gene, which maps on the X chromosome (OMIM 305900), could theoretically be due to a linkage with a predisposing gene located near the G6PD locus." (PMID 34884340, 2021). "The downregulated of G6PD in the asthma group was confirmed using ELISA experiment." (PMID 33194371, 2020). "Our investigation also identified important genes involved in ferroptosis and asthma, including EPAS1, STAT3, G6PD, CYBB, and CBS." (PMID 40165005, 2025).
asthma (continued). "Regarding their siblings, three (0.6%) brothers had G6PD, and each was reported in one (0.2%) brother; down syndrome, cardiac condition, EEG changes, asthma, febrile convulsions, and a brother died at four months of age with achondroplasia." (PMID 37322509, 2023). "In total, 455 cases (asthma-positive) and 11,374 controls (asthma-negative) were compared for G6PD status using multivariable analysis, adjusting for all covariates." (PMID 34884340, 2021). "Lacking G6PD will increase the products of cellular reactive oxygen species, which strengthens those kinase pathways to facilitate viral replication, thus inducing or aggravating asthma." (PMID 33194371, 2020).